PARP9 (poly(ADP-ribose) polymerase family member 9)
Description:
ADP-ribosyltransferase which, in association with E3 ligase DTX3L, plays a role in DNA damage repair and in immune responses including interferon-mediated antiviral defenses. Within the complex, enhances DTX3L E3 ligase activity which is further enhanced by PARP9 binding to poly(ADP-ribose). In association with DTX3L and in presence of E1 and E2 enzymes, mediates NAD(+)-dependent mono-ADP-ribosylation of ubiquitin which prevents ubiquitin conjugation to substrates such as histones. During DNA repair, PARP1 recruits PARP9/BAL1-DTX3L complex to DNA damage sites via PARP9 binding to ribosylated PARP1. Subsequent PARP1-dependent PARP9/BAL1-DTX3L-mediated ubiquitination promotes the rapid and specific recruitment of 53BP1/TP53BP1, UIMC1/RAP80, and BRCA1 to DNA damage sites. In response to DNA damage, PARP9-DTX3L complex is required for efficient non-homologous end joining (NHEJ); the complex function is negatively modulated by PARP9 activity. Dispensable for B-cell receptor (BCR) assembly through V(D)J recombination and class switch recombination (CSR) (By similarity). In macrophages, positively regulates pro-inflammatory cytokines production in response to IFNG stimulation by suppressing PARP14-mediated STAT1 ADP-ribosylation and thus promoting STAT1 phosphorylation. Also suppresses PARP14-mediated STAT6 ADP-ribosylation.
Synonyms: ARTD9; BAL; BAL1; MGC:7868
Tractability: PROTAC: ubiquitination databases record sites on it; its protein half-life has been measured; a small molecule that binds it is known.
Target class: Enzyme; Transferase
Gene: Protein-coding gene on chromosome 3 (122,527,910 to 122,565,478, reverse strand). Ensembl gene ENSG00000138496.
Subcellular location: Cytoplasm, cytosol; Nucleus
Subcellular location (Human Protein Atlas): Cytosol; Nucleoplasm; Mitochondria
Pathways (Reactome):
Disease: Maturation of nucleoprotein
Metabolism: Nicotinate metabolism
Gene Ontology:
Molecular function: ADP-D-ribose binding; enzyme binding; enzyme inhibitor activity; histone binding; NAD+ binding; NAD+ poly-ADP-ribosyltransferase activity; NAD+-protein-C-terminal glycine ADP-ribosyltransferase activity; protein binding; STAT family protein binding; transcription corepressor activity; ubiquitin-like protein ligase binding
Biological process: DNA damage checkpoint signaling; double-strand break repair; negative regulation of catalytic activity; negative regulation of gene expression; negative regulation of transcription by RNA polymerase II; positive regulation of chromatin binding; positive regulation of defense response to virus by host; positive regulation of DNA-templated transcription; positive regulation of protein localization to nucleus; positive regulation of type II interferon-mediated signaling pathway; positive regulation of tyrosine phosphorylation of STAT protein; post-transcriptional regulation of gene expression; protein poly-ADP-ribosylation; regulation of response to type II interferon; cell migration; nicotinate metabolic process; viral protein processing; positive regulation of cytokine-mediated signaling pathway; regulation of type II interferon-mediated signaling pathway
Cellular component: cytoplasm; cytosol; membrane; nucleoplasm; nucleus; protein-containing complex; site of DNA damage
Genetic constraint (gnomAD): Loss-of-function variants: 45 observed, 70.31 expected, observed/expected ratio (o/e) 0.64, 90% interval 0.5 to 0.82. The upper end of that interval is the gene's LOEUF score, 0.82, which puts it in group 3 of 6, group 1 being the genes least tolerant of losing a copy. Missense variants: 797 observed, 1,013.7 expected, observed/expected ratio (o/e) 0.79, 90% interval 0.74 to 0.83. Synonymous variants: 308 observed, 351.09 expected, observed/expected ratio (o/e) 0.88, 90% interval 0.8 to 0.96.
Homologues: Orthologues: chimpanzee PARP9 (99% identical), macaque PARP9 (91% identical), pig PARP9 (67% identical), dog PARP9 (66% identical), rabbit PARP9 (66% identical), mouse Parp9 (62% identical), rat Parp9 (60% identical), guinea pig PARP9 (51% identical), tropical clawed frog parp9 (35% identical), zebrafish parp9 (21% identical). Paralogues in human: PARP14 (28% identical), PARP15 (15% identical), ZC3HAV1 (12% identical), PARP10 (11% identical), PARP12 (10% identical), TIPARP (8% identical), PARP11 (6% identical), ZC3HAV1L (3% identical).
Diseases named in the same sentence as PARP9 in open-access papers:
PARP9 is named in the same sentence as 68 diseases in open-access papers, as found by Europe PMC text mining. Sharing a sentence is not in itself a finding about the gene and the disease. The quoted sentences say what the papers report.
diffuse large B-cell lymphoma (17 papers, 2010 to 2025). "PARP9, also known as B-aggressive lymphoma-1 (BAL1), was identified as a risk-related gene product in aggressive diffuse large B-cell lymphoma (DLBCL) and associated with interferon-gamma (IFNγ) gene expression and signalling." (PMID 39189367, 2024). "PARP9 was originally identified as a gene conferring risk for diffuse large B-cell lymphoma and named BAL1 (B-aggressive lymphoma 1)." (PMID 20942953, 2010). "PARP9 was initially described as a risk factor in diffuse large B-cell lymphoma (DLBCL) and is upregulated in chemoresistant DLBCL." (PMID 35536484, 2022). "Furthermore, in high‐risk diffuse large B cell lymphoma, PARP9 might be related to lymphocyte migration and promote malignant B cell dissemination." (PMID 32678519, 2020). "PARP9 (BAL1) was identified in a genome-wide search for risk-related genes in chemo-resistant diffuse large B-cell lymphoma (DLBCL), the most common non-Hodgkin lymphoma." (PMID 30991935, 2019). "PARP9, originally known as B-aggressive lymphoma-1 (BAL1), was identified as a risk-associated gene in aggressive diffuse large B-cell lymphoma (DLBCL)." (PMID 40741921, 2025). "PARP9 is also known as BAL1 (B aggressive lymphoma-1 protein), a risk factor whose overexpression prevented IFN-induced apoptosis in aggressive diffuse large B-cell lymphoma DLBCL." (PMID 38182103, 2024). "It has been found over-expressed and to bind Parp9 (BAL1) in Diffuse Large B-Cell Lymphoma (DCBCL)." (PMID 37443713, 2023). "PARP9 mediates proliferation, survival and chemo-resistance in diffuse large B-cell lymphoma (DLBCL)." (PMID 39497715, 2024). "PARP3 and PARP9 are overexpressed in different human cancer tissues such as BC, cervical cancer (CC), and diffuse large B-cell lymphoma (DLBCL), whereas PARP7 expression is decreased in cancer tissues." (PMID 34976832, 2021). "PARP9, also termed BAL1 (B-aggressive lymphoma), is expressed at significantly higher levels in fatal high-risk diffuse large B-cell lymphoma (DLBCL) than in low-risk tumors." (PMID 34976832, 2021). "Previous studies have shown that PARP9 is overexpressed in a series of solid tumors, such as breast tumors, prostate tumors, diffuse large B cell lymphomas, and cervical tumors, and PARP9 may promote metastasis, recurrence and chemotherapy resistance in these tumors." (PMID 32678519, 2020). "BAL1, also known as PARP9, was initially identified in the diffuse large B cell lymphoma due to its capacity to enhance the migration of malignant B cells." (PMID 40707929, 2025). "In addition, the expression of PARP9 is regulated by the IFNγ-JAK2/STAT1-IRF1 signaling axis that is required for cancer cell survival in diffuse large B-cell lymphoma (DLBCL) with an active host inflammatory response." (PMID 34725336, 2021). "PARP9 was identified as overexpressed in chemoresistant, diffuse large B-cell lymphomas (DLBCLs), but there is no data concerning the implication of PARP9 in CC." (PMID 23865481, 2013). "DTX3L was originally identified as a binding partner of BAL1 (PARP9/ARTD9), which is an oncogenic factor in diffuse large B-cell lymphoma (DLBCL) with a prominent immune/inflammatory infiltrate." (PMID 36614304, 2023). "The expression of PARP9 is controlled by the IFNγ-JAK2-STAT1-IFN regulatory factor 1 signaling pathway, which is essential for the survival of cells in diffuse large B-cell lymphoma (DLBCL), where the host inflammatory response is activated." (PMID 35652091, 2022).
viral infection (15 papers, 2018 to 2025). "Parp9 and Dtx3l have been recently implicated in enhancing interferon signaling and controlling viral infection." (PMID 31057555, 2019). "Therefore, while studies have implicated PARP9 as a positive regulator of IFNs in viral infections, our results suggest a protective function during TB for PARP9 mediated by limiting IFN production." (PMID 37200107, 2023). "In this manner, this study demonstrated that PARP9 could be depressed by the same phenomenon causing anti‐inflammatory macrophage depletion and poor interferon signaling leading to weak host defense against viral infections." (PMID 33913542, 2021). "In viral infections, the interaction between PARP9 and DTXL3 appears to yield an antivirus effect by promoting the efficacy of type I IFN signaling." (PMID 37200107, 2023). "This condition showed that the SARS-CoV-2 Nsp3 protein is similar to PARP9 and can inhibit PARP9 through molecular mimicry, depleting M2 macrophages, and weakening interferon signaling, which then weakens the ability of the host to resist viral infection." (PMID 36212830, 2022). "On the other hand, PARP9 is an important molecule that provides protection against lethal viral infections through interferon responses, and as PARP14, also participates in the polarization of macrophages towards the M2 phenotype." (PMID 33913542, 2021). "This is of particular importance given that PARP14 has been reported to have a crucial role in responding to coronavirus infection and mediating inflammation, while PARP9/DTX3L has been indicated in controlling viral infection and protecting against Mycobacterium tuberculosis." (PMID 38834853, 2024). "Our findings therefore establish a role for PARP9 that is contrary to its role in viral infections." (PMID 37200107, 2023). "Thus, in sharp contrast to PARP9 enhancement of type I IFN production in viral infections, this member of the MAR family plays a protective role by limiting type I IFN responses during TB." (PMID 37200107, 2023). "PARP9 orchestrates type I IFN responses in viral infections, but its functional role in IFN and myeloid responses during TB disease is unknown." (PMID 37200107, 2023). "This aspect of the findings makes the study increasingly significant, and present a scenario in which one could consider therapeutic targeting of PARP9 signaling to treat virus infection and avoid enhancing an inflammatory cytokine storm." (PMID 33976210, 2021). "PARP9 in viral infections have been associated with promoting type I IFN–mediated antiviral immunity However, a key finding in our in vivo and in vitro studies using a highly relevant bacterial pathogen such as M. tuberculosis showed a contrasting role for PARP9 in M. tuberculosis host immunity." (PMID 37200107, 2023). "PARP9 and DTX3L form a tight complex that has suggested roles in DNA repair, as well as in the response to bacterial or viral infection and carcinogenesis." (PMID 38834853, 2024). "PARP9 mediates the production of type I interferon after binding to viral RNA by activating the PI3K/AKT3 signaling pathway, thereby protecting against viral infection." (PMID 36212830, 2022). "Similar to PARP9, as an important host interferon-stimulated gene in antiviral infection, MX1 (cg25888371) is hypomethylated in CpG after viral infection and then participates in regulating the defense response of the host to infection." (PMID 36212830, 2022). "Next, given that DTX3L is an active E3 ubiquitin ligase and that PARP9 and DTX3L have been reported to regulate ubiquitination in response to viral infection, we also investigated if we could observe any changes to ubiquitination after IFN treatment." (PMID 38834853, 2024). "Interestingly, proteomics directly revealed details on the immune defense against viral infections, including drastic increase in antigen CD177, Integrin alpha‐M (ITGAM) as well as the complex‐forming E3 ubiquitin‐protein ligase DTX3L and PARP9." (PMID 37519267, 2023).
viral infection (continued). "A variety of genes such as OAS2, PARP9, OASL, IFIT2, IFI3, CCL8, CXCL10, etc., were highly upregulated and correlated with high viral load, suggesting that innate immune response genes were activated in a viral load dose response manner to control the viral infection." (PMID 37333115, 2023). "By contrast, there was no colocalization between p85 and PARP9 without viral infection." (PMID 33976210, 2021). "Indeed, recent evidence indicates that PARP9 can act as a noncanonical RNA sensor that depends on the PI3K/AKT3 pathway and deltex 3/histone 2BJ to promote type I IFN production after viral infections with clinical implications." (PMID 37200107, 2023).
glioma (10 papers, 2020 to 2025). A benign or malignant brain and spinal cord tumor that arises from glial cells (astrocytes, oligodendrocytes, ependymal cells). "An enquiry into the functional status of biomarkers in glioma showed that PARP9 was positively associated with EMT, cell metastasis and cell differentiation and negatively associated with DNA damage." (PMID 36778644, 2023). "As one of the PARP family, PARP9 was highly expressed in gliomas and high PARP9 expression was associated with poor prognosis and clinicopathological features, which supported our findings." (PMID 36778644, 2023). "PARP9 is highly expressed in glioma, and high expression of PARP9 is associated with poor prognosis and advanced clinicopathological features." (PMID 32678519, 2020). "High PARP9 expression is associated with advanced clinicopathological parameters and predicts much worse survival for glioma patients." (PMID 32678519, 2020). "Moreover, the PARP9 expression level increased with glioma grade and was associated with clinicopathological parameters (age, vital status, tumor status, histological type, KPS, and IDH1 status)." (PMID 32678519, 2020). "Studies have shown that PARP9 is highly expressed in glioma tissues compared to normal brain tissue, and its high expression is associated with poor prognosis and advanced clinicopathological features." (PMID 40338274, 2025). "PARP9 (poly(ADP-Ribose) polymerase family member 9) has been identified as a potential biomarker and therapeutic target for gliomas." (PMID 40338274, 2025). "Research has demonstrated that PARP9 gene, highly expressed in glioma, is correlated with checkpoint molecules involved in inflammatory and immune responses." (PMID 38982354, 2024). "According to the results of qRT-PCR, the mRNA expressions of CD38, NADK, PARP9 were significantly elevated in glioma tissues compared with NBT, while the mRNA expressions of NAPRT and PARP6 showed a significant downward trend in glioma tissues." (PMID 36845744, 2023). "Apart from the B2M was abnormally upregulated, other recent reported molecules such as NUSAP1, Paxillin, CAVIN1, and PARP9 also overexpressed in glioma tissues." (PMID 33960680, 2021). "The clinicopathological information of patients with glioma in the TCGA database and gene expression profiles were analyzed to determine the relationship between the expression of PARP9 and clinicopathologic characteristics." (PMID 32678519, 2020). "It was determined that PARP9 significantly predicted overall survival in all‐grade gliomas and GBMs." (PMID 32678519, 2020). "In this study, the expression of PARP9 was identified to be upregulated in glioma samples using the TCGA and GEO databases." (PMID 32678519, 2020). "Certainly, other laboratory research should also be undertaken to expound the exact mechanism of PARP9 overexpression in gliomas and explain its correlation with immunomodulation and poor outcome in gliomas." (PMID 32678519, 2020). "Increased PARP9 expression was found to be significantly related to advanced clinicopathologic characteristics and poor prognosis in glioma patients." (PMID 32678519, 2020). "All these results indicate that the expression of PARP9 is closely correlated with the development and malignant progression of glioma." (PMID 32678519, 2020). "Univariate and multivariate Cox analyses were performed to further explore the prognostic value of PARP9 in glioma." (PMID 32678519, 2020). "In this article, we aimed to reveal the relationship between PARP9 and glioma and explore the potential prognostic value and immunotherapeutic targetability of PARP9 in glioma." (PMID 32678519, 2020). "An interesting and novel finding in our study was that PARP9 was involved in the glioma immune microenvironment." (PMID 32678519, 2020).